BRAF (B-Raf proto-oncogene, serine/threonine kinase)
Diseases named in the same sentence as BRAF in open-access papers (continued):
Sharing a sentence is not in itself a finding about the gene and the disease.
melanoma (continued). "Our results indicate that quantitative analysis of BRAF V600mut ctDNA in plasma holds promise as a monitoring tool in BRAF V600 mutant melanoma during treatment with BRAF/MEK targeted therapy." (PMID 27095081, 2016). "For these studies we selected BLM and A375 human melanoma cell lines, representative of the most frequent genetic mutations in melanomas (NRAS and V600E BRAF in BLM and A375 cells, respectively)." (PMID 27461002, 2016). "Of great interest, NS1 treatment was also effective in melanoma cells resistant to treatment with a BRAF inhibitor as suggested by preliminary results." (PMID 27756874, 2016). "Here, we show that in BRAF-mutant melanoma cells, PLX4032 induces c-Jun activation resulting in RHOB expression and subsequent AKT activation." (PMID 26098773, 2015). "Inhibiting the MAPK pathway in BRAFV600-mutant melanoma patients with BRAF inhibitors (vemurafenib and dabrafenib) or a MEK inhibitor (trametinib) has improved progression-free and/or overall survival compared to conventional chemotherapy." (PMID 25537510, 2015). "The survival benefit of combined BRAF and MEK inhibition, not only patients with MM but also those with operable BRAF mutation-positive melanoma has been reported previously." (PMID 26143635, 2015). "It is of interest to note that somatic mutations in the BRAF and NRAS gene are mutually exclusive, thus constitutive activation of the MAPK pathway occurs in approximately 65–75% of all melanoma tumors." (PMID 26426340, 2015). "As it has been shown in BRAF mutant melanomas, resistance to blocking of the MAPK pathway can be the result of reactivation of the same pathway or activation of alternative pathways." (PMID 25645078, 2015). "Recently, combinations of BRAF inhibitors and immunotherapies have shown improved efficacy treating melanoma tumors and are being investigated in clinical trials." (PMID 26262134, 2015). "The development of targeted therapies such as selective BRAF inhibitors has improved the response rate, the progression-free survival and the overall survival of patients with metastatic BRAF-mutant melanomas." (PMID 26204954, 2015). "Our results conclusively establish that overexpression of Mcl-1 is critical for melanoma cell survival in the setting of BRAF inhibitor treatment and induce clinical resistance to BRAF inhibitors." (PMID 26497853, 2015). "He showed us how the history of melanoma treatment has changed since the discovery of BRAF as an oncogene in cancer." (PMID 25932043, 2015). "Because dabrafenib and trametinib can also inhibit the growth of non-BRAF-transformed cells, we investigated if their synergy also occurs in the BRAF-wild type MeWo melanoma cell line." (PMID 26018524, 2015). "The secondary objectives included ORR in patients with BRAF V600K-mutant melanoma, PFS, OS, duration of response, and characterization of the safety profile of dabrafenib." (PMID 26171394, 2015). "In this context, it is intriguing that in melanoma cells, BRAF suppresses FOXD3, which would allow MITF expression to prevail." (PMID 25818589, 2015). "In BRAF mutant melanomas, over-activity of alternative pathways, such as PI3K/AKT, can induce resistance to the inhibitors of the MAPK pathway." (PMID 25645078, 2015). "Altogether, these findings support a potential role for RHOB as a predictive biomarker to PLX4032 therapy and the c-Jun/RHOB/AKT signaling axis as a new target to prevent resistance to BRAFi of BRAF-mutant melanoma tumors." (PMID 26098773, 2015). "This classification led to the identification of a new melanoma subtype displaying intrinsic resistance to targeted therapy against mutant BRAF." (PMID 25742786, 2015). "The occurrence of BRAF_CN as the second ranking member in this set is consistent with strong literature support for the PLX4720-related compound vemurafenib targeting BRAF in the treatment of melanoma." (PMID 26132924, 2015).
melanoma (continued). "Concurrent inhibition of BRAF and glycolysis or autophagy was demonstrated as good methods to induce cell death or tumor regression, respectively, in BRAFi-resistant melanoma." (PMID 25763355, 2015). "In this study we demonstrate that inhibition of mutant BRAF in melanoma cells with pharmacological inhibitors or siRNA knockdown results in the activation of the c-Jun/RHOB/AKT signaling axis, which leads to cell survival." (PMID 26098773, 2015). "A total of 349 patients were analyzed for BRAF mutation by both Sanger sequencing and real-time PCR (Cobas 4800 BRAF V600 Mutation Test), including 181 cases of CRC, 127 cases of PTC and 41 cases of malignant melanoma." (PMID 25784606, 2015). "Several of these sites were substrates for CK2A, and we tested if long-term exposure to BRAFi provided protection from the synergistic inhibitory effects of protein kinase CK2A–BRAF co-inhibition previously observed in BRAF(V600E) mutant melanoma." (PMID 26029660, 2015). "In particular, a recent report demonstrated an important role of SGK3 in promoting mutant BRAF melanoma growth." (PMID 26573229, 2015). "Currently, therapy used for the treatment of vemurafenib resistant melanoma involves combination BRAF and MEK inhibitors to target inhibition of the MAPK pathway." (PMID 26139106, 2015). "Coexistence of high MITF expression levels and BRAF mutations is able to transform human melanocytes; thus, MITF can function as a melanoma oncogene." (PMID 26322273, 2015). "Our studies provided several in vitro and in vivo evidences to prove this and established Mcl-1 as the major culprit in inducing resistance to BRAF inhibitors in melanoma." (PMID 26497853, 2015). "A recent study of Aurora A kinase inhibitor MLN8054, MEK inhibitor trametinib, and BRAF inhibitor dabrafenib evaluated various combinations of these drugs in BRAF mutant melanoma cell lines." (PMID 26136684, 2015). "Our data suggests that vemurafenib induces OXPHOS in BRAF mutant melanoma cells, making it a good combination drug for BAY 87-2243." (PMID 26500770, 2015). "We here assessed the prevalence of the coexistence of BRAF/NRAS and PIK3CA mutations in a series of melanoma samples." (PMID 25627962, 2015). "The combination of BRAF-targeted therapy with CSF-1R blockade resulted in increased CD8 T-cell responses in the SM1 melanoma model, supporting the ongoing evaluation of this therapeutic combination in patients with BRAFV600 mutant metastatic melanoma." (PMID 25939769, 2015). "Combined MEK and BRAF inhibition has proven beneficial in the clinic to overcome ERK-dependent acquired resistance in BRAF-mutant melanoma patients." (PMID 26137449, 2015). "Analysis of signal pathways in melanoma cell lines resistant to BRAF inhibitors revealed that treatment with the combination strongly downregulated anti-apoptotic proteins and proteins in the AKT and Hippo/YAP signaling pathways." (PMID 26087189, 2015). "Changes in the phosphoproteome of a BRAF(V600E) mutant melanoma cell line that occur after the development of drug (PLX4720) resistance in vitro are described here." (PMID 26029660, 2015). "Combination therapy with the CSF-1R inhibitor PLX3397 and the oncogenic BRAF inhibitor vemurafenib result in superior antitumor effects compared to single agent treatment in a murine model of melanoma." (PMID 25939769, 2015).
melanoma (continued). "Despite these data that suggest BRAFV600 mutations are heterogeneous, the clinical response to BRAF inhibitors is homogenous and suggests that the BRAFV600 mutation is relevant in the majority of melanoma cells." (PMID 26498143, 2015). "A review of literature reports that 14 % of mucosal melanomas harbor activating c-KIT mutations; 5 % showed BRAF mutation and 14 % oncogenic mutations in NRAS, which is much lower than the reported BRAF prevalence (56–59 %) in cutaneous melanoma." (PMID 26420268, 2015). "As a consequence, the combination of both inhibitors augmented the anti-tumor effect of BAY 87-2243 in a BRAF mutant melanoma mouse xenograft model." (PMID 26500770, 2015). "Mutational analyses have recently enabled the detection of up to 50% of malignant melanomas carrying an activating mutation in BRAF, and these can now be treated with specific B-RAF inhibitors." (PMID 26327537, 2015). "Combining vemurafenib with an mTOR or PI3K inhibitor improved cell killing in BRAF-mutant melanomas with ERK-independent resistance to MAPK inhibition." (PMID 26639561, 2015). "Inhibition of the EGF receptor and Src re-sensitizes treatment-resistant BRAF-mutant melanoma cells to Vemurafenib and blocks their invasiveness." (PMID 25763355, 2015). "Oncogenic BRAF(V600E) sensitized the melanoma cells to exposure to doses of UVB that would be expected to result in only mild erythema in most Caucasians." (PMID 26091525, 2015). "We have previously demonstrated that CK2 plays an important role in priming the activity of Akt through phosphorylation at S129, and that controlling CK2 activity is an effective strategy in preventing cell growth in BRAF melanoma and BRAF thyroid carcinoma." (PMID 26029660, 2015). "Overall, in BRAF mutant/MITF‐positive melanoma cells, a BRAF/BRN2 rheostat appears to control MITF basal expression levels." (PMID 25818589, 2015). "In melanoma, constitutive activation of the BRAF/MEK/ERK (MAPK) and PI3K/AKT/mTOR (PI3K) signaling pathways plays a pivotal role in cell proliferation, survival and tumorigenesis." (PMID 26299806, 2015). "Our data show that BAY 87-2243 has substantial effects as a single agent against melanoma in vitro and in vivo, including BRAF mutant melanoma." (PMID 26500770, 2015). "Melanoma exhibits elevated levels of ER stress and autophagy following treatment with the specific BRAF inhibitor, PLX4720." (PMID 26622781, 2015). "Several miRNA were reported as regulators of BRAF in different cancers such as miR-524-5p in melanoma, miR-143 and miR-145 in CRC." (PMID 25977643, 2015). "Our group has previously reported that BRAF expression is increased in primary and metastatic melanomas and predicts worse survival in patients with primary melanoma." (PMID 25784655, 2015). "Taken together these results suggest that Sema6A and Plexin-A4 have distinct roles in regulating biological functions in BRAF-mutant melanoma cells." (PMID 25576923, 2015). "Among the analysed melanomas, 12/245 (4.9%) samples presented the coexistence of PIK3CA and BRAF/NRAS mutations." (PMID 25627962, 2015). "The EGFR/SFK/STAT3 signaling axis was found to be up-regulated in BRAF-resistant melanoma cell lines and in patients with intrinsic or who developed acquired resistance to Vemurafenib." (PMID 26393652, 2015). "The primary endpoint of the study was to measure ORR (either complete response or partial response assessed by an investigator) in patients with BRAF V600E-mutant melanoma." (PMID 26171394, 2015). "In this light, combining the MEK inhibitor trametinib with BRAF inhibitors in melanoma treatments has resulted better clinical outcomes than either therapy alone." (PMID 26370727, 2015). "Using RT-qPCR screening, we detected a significant induction of RHOB expression upon PLX4032 treatment in BRAF-mutant melanoma cells." (PMID 26098773, 2015).
melanoma (continued). "Among the 36 patients with BRAF V600-mutant melanoma being administered the recommended dose, 18 (50%, 32.9–67.1) had confirmed response and the rate for patients with BRAF V600E was 56% (15 out of 27, 56%, 35.3–74.5)." (PMID 26171394, 2015). "Mcl-1 targeted therapies will have significant impact on the patients with melanoma tumors refractory to BRAF inhibitors alone or in combination with MEK1/2 inhibitor." (PMID 26497853, 2015). "Three patients (all melanoma) had plasma collection immediately after coming off BRAF or MEK targeted therapy and 1 patient (appendiceal cancer) had plasma collection right after being taken off standard chemotherapy without evidence of disease progression." (PMID 25980577, 2015). "In fact, the selective mutant BRAFV600E inhibitor vemurafenib actively reduced glucose uptake in BRAF mutant melanoma cell lines." (PMID 26500770, 2015). "In this study, we tested the telomerase-based assay’s ability to identify melanoma cells in culture and CTCs in patients with melanoma, as well as its ability to enable genetic analysis of such cells, particularly mutant BRAF status." (PMID 25807549, 2015). "Mutations in BRAF, GNA11, GNAQ, KIT, MEK1 (MAP2K1), and NRAS can be found in approximately 70% of all melanomas." (PMID 26101870, 2015). "A total of 35 patients had concordantly BRAF-positive and 36 (48%) patients had concordantly BRAF-negative primary melanomas and matched metastases The four (5%) remaining patients each had one BRAFV600-positive and one BRAFV600-negative sample." (PMID 26498143, 2015). "Using BRAF mutant melanoma as a model system, we here report that BAY 87-2243-mediated complex I inhibition induced melanoma cell death in vitro and reduced melanoma tumor growth in various mouse models in vivo." (PMID 26500770, 2015). "We believe, based on our data that one of these master regulators in mutant BRAF melanomas, is indeed the ErbB3 receptor." (PMID 26208478, 2015). "Mutations associated with RAF family (A-Raf, B-Raf, and C-Raf) are mainly associated with the BRAF gene and are found in a variety of cancers with high frequency in malignant melanoma, thyroid and colon carcinoma." (PMID 26404379, 2015). "In this model, we observed that adoptive cell transfer (ACT) of melanoma-targeted T-cells induces antitumor responses that are augmented by the BRAF inhibitor PLX4032." (PMID 25939769, 2015). "This is particularly relevant with the shifting practice of combining BRAF inhibitors with selective MEK inhibitors in BRAF V600-mutant melanoma patients." (PMID 25991583, 2015). "The first evidence for stroma-mediated drug resistance in melanoma came from studies demonstrating the role of stroma-derived hepatocyte growth factor (HGF) in BRAF inhibitor resistance." (PMID 26622938, 2015). "This clinical trial indicated that nivolumab represented a new treatment option for the patients with advanced melanoma that has progressed after ipilimumab or ipilimumab and a BRAF inhibitor." (PMID 26305724, 2015). "In BRAF-mutated melanoma, the MAPK pathway cooperates with PI3K signaling to promote melanoma initiation and progression." (PMID 26299806, 2015). "In order to test the in vivo efficacy of BAY 87-2243 and vemurafenib as single agents and in combination, we used the inhibitors in a BRAF mutant melanoma cell xenograft model." (PMID 26500770, 2015). "Another study found rearrangements in gastric, prostate cancer and melanoma that involve again fusions containing BRAF or RAF1 segments." (PMID 25473895, 2015). "Taken together, our results suggest RTK mediated signaling is an adaptive response to mutant BRaf inhibition in melanomas and suggests combination therapy with specific RTK inhibitors to have potential clinical benefit." (PMID 26405815, 2015). "In this pilot study, we investigated patients with advanced melanoma who were responders on clinical trials using BRAF and/or MEK inhibitors." (PMID 25886620, 2015).
melanoma (continued). "Our study further suggests that PIK3CA mutations account for a small fraction of PI3K pathway activation and have a limited impact in interfering with the BRAF/NRAS-driven growth in melanoma." (PMID 25627962, 2015). "A recent study reported improved antitumor response in a mouse model of melanoma using BRAF and MEK inhibitors in combination with immunotherapy." (PMID 26299805, 2015). "Next, we used the curve shift method to study the combination of the MEK inhibitor trametinib and the BRAF inhibitor dabrafenib, which has shown synergistic activity in BRAF-mutant melanoma cell lines, and in melanoma patients." (PMID 26018524, 2015). "First we examined ZA’s short-term (72 h) effect on melanoma cells with various NRAS, BRAF and PTEN mutation status, but the role of these mutations on treatment response was not equivocal." (PMID 25646931, 2015). "Having previously found six independent prognostic biomarkers in melanoma, including BRAF, MMP2, p27, Dicer, Fbw7 and Tip60, our group has gone on to investigate if these markers are useful in risk stratification of melanoma patients in individual AJCC stages." (PMID 25784655, 2015). "In line with this, BRN2 increases transcription from the MITF promoter in a panel of BRAF mutant melanoma cells." (PMID 25818589, 2015). "Patients with NRAS mutant melanomas had thicker tumors at presentation and these tumors had greater rates of mitosis than BRAF mutant and WT melanoma." (PMID 26305188, 2015). "Recent studies have highlighted that mutant BRAF inhibition makes melanoma cells dependent on OXPHOS and mitochondrial ATP production." (PMID 26500770, 2015). "Several studies have demonstrated that mutant BRAF regulates secretion of pro-angiogenic factors, enhances growth and increases the development of vasculature in melanoma tumors." (PMID 26299806, 2015). "This approach of intermittent therapy targeting BRAF in melanoma has been partially examined by the use of a schedule of 3 weeks on and 1 week off of the MEK inhibitor cobimetinib when combined with the BRAF inhibitor vemurafenib that is given continuously." (PMID 26236691, 2015). "Accordingly, a recent study shows that miR146a, upregulated by oncogenic BRAF, promotes the initiation and progression of melanoma cells through down-regulation of NUMB." (PMID 25986346, 2015). "Our results extended this observation by showing that SGK3 similarly played a role in proliferation of wild-type BRAF melanoma cells (Mel-RM and ME4405) and melanocytes, at least when the upstream signal was driven by INPP4B." (PMID 26573229, 2015). "The patient was suffering from known pulmonary, hepatic, subcutaneous and bone metastases 21 months after the initial diagnosis and excision of a malignant melanoma on the helix of the right auricle (Clark Level 2, BRAF status: V600E positive)." (PMID 26187589, 2015). "We predicted through quantitative simulations that melanoma cells were arrested in G1-phase of the cell cycle when c-Myc was targeted alone or in combination with other proteins, particularly BRAF, MEK, and cyclin D1." (PMID 26284497, 2015). "For example, exogenous MITF overexpression has been shown to repress the ability of BRaf inhibition to kill melanoma and in cells that display high MITF activity, class III and class IV melanosomes can sequester drugs." (PMID 26405815, 2015). "Since BRAF and NRAS mutations are mutually exclusive in nearly all cases, it is widely recognized that about two-thirds of patients present a melanoma with activation of the MAPK pathway, carrying a mutated BRAF or NRAS gene." (PMID 26322273, 2015). "The selective BRAF inhibitor vemurafenib has demonstrated clinical efficacy in patients with BRAF V600E-mutant melanoma brain metastases (MBM)." (PMID 25991583, 2015). "Based on the predictions from the data-driven network models, we found that co-targeting MEK or BRAF with c-Myc leads to synergistic responses that render a melanoma cell line more sensitive to inhibition of BRAF." (PMID 26284497, 2015).